CUL5 (cullin 5)
Description:
Core component of multiple cullin-5-RING E3 ubiquitin-protein ligase complexes (ECS complexes, also named CRL5 complexes), which mediate the ubiquitination and subsequent proteasomal degradation of target proteins. Acts a scaffold protein that contributes to catalysis through positioning of the substrate and the ubiquitin-conjugating enzyme. The functional specificity of the E3 ubiquitin-protein ligase complex depends on the variable SOCS box-containing substrate recognition component. Acts as a key regulator of neuron positioning during cortex development: component of various SOCS-containing ECS complexes, such as the ECS(SOCS7) complex, that regulate reelin signaling by mediating ubiquitination and degradation of DAB1 (By similarity). ECS(SOCS1) seems to direct ubiquitination of JAK2. The ECS(SOCS2) complex mediates the ubiquitination and subsequent proteasomal degradation of phosphorylated EPOR and GHR. The ECS(SPSB3) complex catalyzes ubiquitination of nuclear CGAS. ECS(KLHDC1) complex is part of the DesCEND (destruction via C-end degrons) pathway and mediates ubiquitination and degradation of truncated SELENOS selenoprotein produced by failed UGA/Sec decoding, which ends with a glycine. The ECS(ASB9) complex mediates ubiquitination and degradation of CKB. As part of some ECS complex, promotes 'Lys-11'-linked ubiquitination and degradation of BTRC. As part of a multisubunit ECS complex, polyubiquitinates monoubiquitinated POLR2A. As part of the ECS(RAB40C) complex, mediates ANKRD28 ubiquitination and degradation, thereby inhibiting protein phosphatase 6 (PP6) complex activity and focal adhesion assembly during cell migration. As part of the ECS(RAB40A) complex, mediates RHOU 'Lys-48'-linked ubiquitination and degradation, thus inhibiting focal adhesion disassembly during cell migration. As part of the ECS(RAB40B) complex, mediates LIMA1/EPLIN and RAP2 ubiquitination, thereby regulating actin cytoskeleton dynamics and stress fiber formation during cell migration. The ECS(ASB7) complex acts a negative regulator of H3K9me3 histone mark by mediating ubiquitination and degradation of SUV39H1. As part of the ECS(LRRC58) complex, mediates CDO1 ubiquitination and degradation, regulating cysteine catabolism. May form a cell surface vasopressin receptor. (Microbial infection) Following infection by HIV-1 virus, CUL5 associates with HIV-1 Vif proteins and forms a cullin-5-RING E3 ubiquitin-protein ligase complex (ECS complex) that catalyzes ubiquitination and degradation of APOBEC3F and APOBEC3G. The complex can also ubiquitinate APOBEC3H to some extent.
Synonyms: CUL-5; VACM-1; VACM1
Tractability: Small molecule: a structure with a bound ligand is known. PROTAC: UniProt records ubiquitination sites on it; ubiquitination databases record sites on it; its protein half-life has been measured.
Gene: Protein-coding gene on chromosome 11 (108,008,898 to 108,107,781, forward strand). Ensembl gene ENSG00000166266.
Subcellular location: Nucleus
Subcellular location (Human Protein Atlas): Cytosol; Golgi apparatus
Pathways (Reactome):
Disease: Evasion by RSV of host interferon responses; Vif-mediated degradation of APOBEC3G
Immune System: Antigen processing: Ubiquitination & Proteasome degradation; Inactivation of CSF3 (G-CSF) signaling
Metabolism of proteins: Neddylation
Signal Transduction: Downregulation of ERBB2 signaling
Gene Ontology:
Molecular function: protein binding; ubiquitin ligase complex scaffold activity; ubiquitin protein ligase binding; calcium channel activity; signaling receptor activity; ubiquitin-protein transferase activity
Biological process: cell migration; negative regulation of focal adhesion assembly; negative regulation of focal adhesion disassembly; proteasome-mediated ubiquitin-dependent protein catabolic process; protein K11-linked ubiquitination; ERBB2 signaling pathway; G1/S transition of mitotic cell cycle; intrinsic apoptotic signaling pathway; positive regulation of cell migration; protein ubiquitination; reelin-mediated signaling pathway; regulation of neuron migration; SCF-dependent proteasomal ubiquitin-dependent protein catabolic process; calcium ion transmembrane transport; signal transduction; ubiquitin-dependent protein catabolic process
Cellular component: Cul5-RING ubiquitin ligase complex; nucleus; site of DNA damage; cytoplasm; cytosol; SCF ubiquitin ligase complex; cullin-RING ubiquitin ligase complex
Genetic constraint (gnomAD): Loss-of-function variants: 14 observed, 43.24 expected, observed/expected ratio (o/e) 0.32, 90% interval 0.21 to 0.51. The upper end of that interval is the gene's LOEUF score, 0.51, which puts it in group 2 of 6, group 1 being the genes least tolerant of losing a copy. Missense variants: 216 observed, 421.15 expected, observed/expected ratio (o/e) 0.51, 90% interval 0.46 to 0.57. Synonymous variants: 164 observed, 149.41 expected, observed/expected ratio (o/e) 1.1, 90% interval 0.97 to 1.25.
Homologues: Orthologues: chimpanzee CUL5 (100% identical), rabbit CUL5 (100% identical), dog CUL5 (99% identical), guinea pig CUL5 (99% identical), tropical clawed frog cul5 (99% identical), rat Cul5 (99% identical), pig CUL5 (99% identical), mouse Cul5 (98% identical), zebrafish cul5a (97% identical), macaque CUL5 (93% identical), Drosophila melanogaster Cul5 (66% identical), Caenorhabditis elegans cul-5 (51% identical). Paralogues in human: CUL4B (28% identical), CUL1 (28% identical), CUL4A (28% identical), CUL2 (26% identical), CUL3 (24% identical), ANAPC2 (14% identical), CACUL1 (6% identical).
Diseases named in the same sentence as CUL5 in open-access papers:
CUL5 is named in the same sentence as 84 diseases in open-access papers, as found by Europe PMC text mining. Sharing a sentence is not in itself a finding about the gene and the disease. The quoted sentences say what the papers report.
lung carcinoma (11 papers, 2012 to 2026). "Furthermore, a genome-wide CRISPR inhibition (CRISPRi) screen conducted in lung cancer cells demonstrated that knockout of CUL5, RBX2, or UBE2F (a specific E2 for CRL5 E3s) caused cells to become hypersensitive to a CDK9 inhibitor or MCL-1 inhibitor." (PMID 40699886, 2025). "Based on our data, patients with lung cancers that exhibit loss of function mutations in either CUL5, RNF7, UBE2F or Elongin B that coincide with high expression of MCL1/Bcl-xL could be good candidates for treatment with CDK9i or MCL1i." (PMID 31294695, 2019). "Consistently, we found that a small molecule neddylation inhibitor of UBE2F-Cullin-5 effectively sensitized lung cancer cells to radiation." (PMID 39762645, 2025). "We next determined the effect of transfected SAG/CUL5 or RBX1/CUL1 on endogenous levels of β-TrCP1 in two lung cancer cell lines, A427 and A549 harboring relatively high levels of β-TrCP1." (PMID 27910872, 2016). "The traditional view is that CUL5 is a potential tumor suppressor that can inhibit the proliferation, migration and invasion of renal cell carcinoma, endometrial carcinoma, prostate cancer, gastric cancer and lung cancer cells and maintains genomic stability." (PMID 36339709, 2022). "UBE2F facilitates CUL5 neddylation and activation, which ubiquitinates and degrades pro-caspase 3, IκBα, and NOXA, thus inducing adaptive radioresistance in lung cancer." (PMID 41540013, 2026). "In lung cancer tissues, high levels of UBE2F and CUL5 correlate with reduced NOXA levels and poorer survival in patients." (PMID 40699886, 2025). "Similarly, CUL5 neddylation enhances CRL5 activity through the UBE2F/SAG/CUL5 complex, thus ubiquitylating NOXA at K11 in the proteasomal degradation pathway in lung cancer." (PMID 41540013, 2026).
cervical carcinoma (9 papers, 2016 to 2026). A carcinoma arising from either the exocervical squamous epithelium or the endocervical glandular epithelium. "CUL5 depletion impedes mitotic exit and enhances the chemosensitivity of cervical carcinoma HeLa cells to paclitaxel by downregulating APC11, in both in vitro cell cultures and in vivo xenograft tumor models." (PMID 41159544, 2026). "For example, miR-19a was reported to play oncogenic role in gastric cancer by targeting the tumor suppressor MXD1,in cervical carcinoma by targeting CUL5 and in pancreatic cancer by downregulating RHOB promote and." (PMID 29416742, 2018). "A significant decrease in CUL5 expression is observed in the majority of breast cancers, while inhibition of CUL5 expression using microRNA-19a and -19b induced cervical carcinoma cell proliferation and invasion." (PMID 29746508, 2018). "CUL5 expression is negatively regulated by miR-19a and miR-19b, which are highly expressed in cervical cancer cells and are important determinants of the malignant phenotype in those cells, a phenotype that was suppressed when CUL5 3′UTR was deleted." (PMID 29594129, 2018). "MiR-19b also contributes to human cervical carcinoma cellular proliferation and invasion through suppressing vasopressin-activated calcium-mobilizing receptor-1 (CUL5)." (PMID 27602768, 2016). "For instance, downregulation of miR-141 increases CUL3 expression in Hirschsprung's disease, and miR-19 targets CUL5 to regulate proliferation and invasion of cervical cancer cells." (PMID 26840256, 2016). "The up-regulation of miR-19a and miR-19b promotes cervical carcinoma cell proliferation and invasion by targeting CUL5." (PMID 27683641, 2016). "Previously, miR-19a-3p was involved in tumorigenesis of cervical carcinoma by targeting CUL5." (PMID 33014522, 2020). "As a target for miR‐19a/b, CUL5 induces proliferation and invasion in cervical cancer cells." (PMID 27239439, 2016). "Moreover, investigating the in vivo crosstalk between CUL5 and APC11 in cancer types beyond pancreatic cancer and cervical carcinoma represents an important and intriguing direction for future research." (PMID 41159544, 2026).
viral infection (9 papers, 2010 to 2025). "Specifically, following viral infection, Cul5 deficient macrophages prevented neutrophilic accumulation in the lung and protected against viral-mediated asthma exacerbation." (PMID 40842987, 2025). "Cullin-5 (Cul-5) has been most extensively studied in the context of viral infection, and has recently been implicated in the regulation of the non-receptor tyrosine kinase Src." (PMID 20140218, 2010). "Together, these data support that CUL5 promotes pro-inflammatory macrophage function following viral infection, and during autoimmune disease development." (PMID 40842987, 2025). "Considering that some viruses hijack Cul5 to degrade antiviral proteins, it might be better to study the function of Cul5 during virus infection." (PMID 27030794, 2016). "However, CUL5 upregulation significantly promoted lung injury and modulated the immune response in terms of cytokine and chemokine induction by both antigen exposure and virus infection." (PMID 38177117, 2024). "CUL5 is an important component of Cullin-RING ligase-5 (CRL-5), which mediates the ubiquitylation and degradation of several key cellular proteins involved in cancers and viral infections." (PMID 37891174, 2023). "Considering the known interaction between cullin-5 and E1B-55K, however, it is probable that the viral protein may disrupt host cullin-RING ubiquitin ligases, a phenomenon observed in many other viral infections as well." (PMID 38140597, 2023). "Collectively, our results demonstrate that CUL5, which is upregulated by the epithelial alarmin TSLP in allergic asthma, can contribute to the “insensitive” state of AMs by inhibiting IFN-β production following the viral infection and driving the development of virus-induced asthma exacerbations." (PMID 38177117, 2024). "Unlike closely related protein family members Cul1, Cul4 and Cul5, which are hijacked by HIV-1 to support viral infection, our data demonstrate that Cul3 acts as a negative regulator of HIV-1 infection and further elucidate the mode of action by which Cul3 exerts this restrictive effect on HIV-1." (PMID 32882949, 2020).
breast cancer (8 papers, 2016 to 2024). A primary or metastatic malignant neoplasm involving the breast. "It has been reported that CUL1, CUL2, CUL4A and CUL5 are efficiently deNEDDylated by MLN4924 in MCF breast cancer cells." (PMID 35880551, 2022). "Many previous studies have analyzed the mechanism of high CUL5 expression in breast cancer and its metastasis." (PMID 34415831, 2021). "Human CUL5 localizes at chromosome 11 to the region at 11q22-23 which is frequently deleted in breast cancer." (PMID 29746508, 2018). "For example, overexpression of CUL5 cDNA in a breast cancer-derived cell line, T47D, inhibited nuclear localization of estrogen receptor ERα and inhibited estrogen-dependent cell growth." (PMID 29746508, 2018). "Nevertheless, no mutation was found at the putative phosphorylation or neddylation site of Cul5 in T47D breast cancer cells, U138MG glioma cells, ACHN renal cancer cells, and OVCAR-3 ovarian cancer cells." (PMID 27030794, 2016). "In addition, following 6 h treatment with MLN4924, CUL1, CUL2, CUL4A and CUL5 are efficiently deNEDDylated in MCF breast cancer cells." (PMID 35880551, 2022). "Mutational analysis of VACM-1/CUL5 exons in cancer cell lines has been performed previously, and T47D breast cancer cells biological activity alongside VACM-1/CUL5 may be regulated by posttranslational modifications." (PMID 34415831, 2021). "CUL5 (VACM-1) is located on chromosome 11q22-q23, a genomic region associated with loss of heterozygosity in breast cancer, and might therefore be considered as a tumor suppressor." (PMID 28163933, 2017). "A reduction of CUL5 expression was found, for instance, in breast cancer, but so far not in prostate carcinoma." (PMID 28163933, 2017). "Overexpression of Cul5 in T47D breast cancer cells decreases cell growth and mitogen activated protein kinase (MAPK) phosphorylation, and Cul5 overexpression downregulates early growth response 1 (EGR-1) protein expression and upregulates Fas-L mRNA expression." (PMID 27030794, 2016). "HER2 breast cancer (BC) cells often exhibit elevated expression of HER2, cell division cycle 37 protein (Cdc37), and Heat shock protein 90 (Hsp90), while the expression of Cullin5 (CUL5) is decreased." (PMID 39223632, 2024).
HIV-1 infection (5 papers, 2007 to 2020). The type species of lentivirus and the etiologic agent of acquired immunodeficiency syndrome (AIDS). "CUL5 polymorphisms in African Americans have been associated with more rapid CD4+ T cell loss following HIV-1 infection." (PMID 23217182, 2012). "No distortion of frequency distribution between risk groups was observed for any SNP or haplotype in AA or EA (unpublished data), suggesting that the CUL5 genetic variation assessed herein has no obvious effect on susceptibility to HIV-1 infection." (PMID 17257057, 2007). "In HIV-1 infected cells, CUL-5, a member of the Cullin family, interacts with HIV-1 protein Vif and functions as an E3 ubiquitin ligase to induce polyubiquitination and proteasomal degradation of host antiviral protein APOBEC3G42, thereby promoting HIV-1 infection." (PMID 29416066, 2018).
AIDS (4 papers, 2007 to 2025). A syndrome resulting from the acquired deficiency of cellular immunity caused by the human immunodeficiency virus (HIV). "We found CUL5 under strong selection in the Biaka; previous genotyping efforts had included an allele associated with delayed AIDS progression, which we found to be present in 100% of Biaka chromosomes, and 96% of Mbuti chromosomes." (PMID 23217182, 2012). "The protective allele of the CUL5 SNP rs11212495, located between exons 4 and 5, which is associated with delayed AIDS progression in African Americans, was found to be fixed across the Biaka." (PMID 23217182, 2012). "We found that the genomic region surrounding the gene CUL5, encoding cullin 5, one of the strongest risk predictors of AIDS progression yet identified by candidate gene analysis, displayed a strong signature of recent selection in the Biaka." (PMID 23217182, 2012). "To understand the role of genetic variation in the gene encoding Cullin 5 on HIV-1/AIDS, we examined 12 SNPs and their haplotypes on risk and progression of HIV-1 disease." (PMID 17257057, 2007). "We examined the effect of genetic polymorphisms in the CUL5 gene (encoding Cullin 5 protein) on AIDS disease progression in five HIV-1 longitudinal cohorts." (PMID 17257057, 2007).
colorectal cancer (4 papers, 2021 to 2026). A primary or metastatic malignant neoplasm that affects the colon or rectum. "At the same time, the knockdown of PRDX1 eliminates etoposide-induced CUL5 neddylation and increases the sensitivity of colorectal cancer cells to etoposide therapy." (PMID 36690633, 2023). "Colorectal cancer cells increase CUL5 neddylation to accelerate NOXA degradation, which prevents etoposide-induced apoptosis." (PMID 36690633, 2023).
gastric cancer (4 papers, 2018 to 2023). A primary or metastatic malignant neoplasm involving the stomach. "CUL5 is widely expressed in the body, including the esophagus, and appears to block the progression of small-cell lung cancer and gastric cancer." (PMID 37891174, 2023). "NOXA, as a substrate for CUL5, underwent neddylation under the mediation of CUL5 and may induce apoptosis of gastric cancer cells." (PMID 37777749, 2023).
prostate carcinoma (4 papers, 2017 to 2022). A carcinoma that arises from epithelial cells of the prostate gland. "Functional assay found that miR-19a promoted cell migration, invasion, EMT, and metastasis in prostate cancer through down-regulation of CUL5, while rescuing CUL5 would partially reverse the roles of miR-19a on prostate cancer." (PMID 34299149, 2021). "In addition, decreased CUL5 expression would predict a worse outcome for prostate cancer patients." (PMID 34299149, 2021). "Likewise, our results suggest a role for cullin 5 (CUL5) in prostate carcinoma." (PMID 28163933, 2017).
allergic asthma (3 papers, 2022 to 2025). A asthma with a basis in a pathological type I hypersensitivity reaction. "As our data showing that CUL5 was upregulated in HDM-induced allergic asthma mice, we speculated that the inhibitory effect of CUL5 on antiviral immunity is caused by the allergic asthma microenvironment." (PMID 38177117, 2024). "Cul5 also influenced allergic asthma by modulating the antiviral immune response of AMs." (PMID 40893770, 2025). "Collectively, our results indicate that TSLP in the allergic asthma microenvironment can induce a CUL5-mediated inhibitory effect on antiviral immunity, which may contribute to the exacerbations of asthma." (PMID 38177117, 2024). "Mice lacking Cul5 in CD4+ T cells showed Th2/Th9 inflammation and allergic asthma features." (PMID 40893770, 2025).